AR (androgen receptor)
Diseases named in the same sentence as AR in open-access papers (continued):
Sharing a sentence is not in itself a finding about the gene and the disease.
cancer (continued). "Our data on SEs bound by the AR expand on the role of SEs recently shown for other cancer types, in some cases allowing for stratification predictive of treatment response." (PMID 32333502, 2020). "Cancer-associated SPOP mutants show reduced binding, ubiquitination and degradation of oncoprotein substrates such as the androgen receptor and the ETS transcription factor ERG." (PMID 32365080, 2020). "Accumulating evidence demonstrated that AR also played key roles in regulating hormone-related cancer progression." (PMID 33082888, 2020). "We found that the cancer cell motility and growth inhibition of brassicasterol was more enhanced after treatment with AR siRNA." (PMID 32972001, 2020). "Many studies have demonstrated that positive AR expression increases cancer cells’ chemotherapy resistance and stem cell-like properties." (PMID 32587770, 2020). "It has been proved that correlative feedback activation of PI3K/AKT and AR signaling pathways let cancer cells to use to one pathway for survival when the other pathway is pharmacologically blocked." (PMID 32972001, 2020). "Although the gene expression level was not statistically meaningful, the detection rates of the three cancer-related genes (AR, AR-V7, and PSMA) were higher with the CTC-μChip, while two genes (KRT19 and CD45) had the same detection rate." (PMID 32961814, 2020). "Recent studies have shown that the androgen receptor (AR) signalling is involved in pathogenicity and progression of cancer." (PMID 33245722, 2020). "A previous study utilizing normal and cancerous human prostate tissues and PCa cell lines demonstrated that YAP1 and AR formed a protein complex in the nucleus of cancer cells under androgen-dependent and -independent conditions." (PMID 32293349, 2020). "According to previous reports, menin-MLL interaction plays a role in multiple cancers due to epigenetic transcriptional regulation and to an essential co-factor role for a number of important master regulators such as AR or ER." (PMID 31947537, 2020). "A recent study revealed the relationship between androgens and HCSC maintenance demonstrating that androgens and AR participated in cancer stem cells (CSCs) regulation through the nanog related pathway, a potent positive regulator of HCC stemness." (PMID 32041983, 2020). "As IL-6 impact on cancer cells increased serine-threonine kinase Pim1, over stimulation also led to AR transcriptional reactivity." (PMID 32961987, 2020). "In particular, it has been shown that 28% of cancers resistant to androgen-deprivation therapy display AR upregulation due to amplification of its gene." (PMID 32085497, 2020). "The AR pathway is another important hormonal pathway and positive IHC staining has been described for different cancer types." (PMID 33613616, 2020). "We outline the involvement of tubulin alterations, androgen receptor (AR) signaling/AR variants, ERG rearrangements, drug efflux/influx, cancer stem cells, centrosome clustering, and phosphoinositide 3-kinase/AKT signaling in mediating DTX resistance." (PMID 35582222, 2020). "AR is proposed to have an inhibitory effect on cancer cells via inhibition of ER activity in ER-positive breast cancers, while AR is suggested to promote the proliferation of cancer cells in ER-negative breast cancers." (PMID 32290220, 2020). "ERa apical staining easily distinguished cancer from normal epithelium in the same field, a feature that was impossible with IHC for AR (asterisks)." (PMID 33266334, 2020). "Univariate and multivariate logistic regression analysis of theassociation between AKT1 and AR genes inprostate cancer patients and controls." (PMID 32484847, 2020).
cancer (continued). "CHK2 mutation or loss of expression in PCa leads to increased AR transcriptional activity, possibly of DDR genes, and survival in response to DNA damage, all leading to a more aggressive cancer." (PMID 32579110, 2020). "We previously reported that telomerase reverse transcriptase (hTERT) and AR were direct targets of SMYD3 in cancers." (PMID 32007952, 2020). "Since AR is a transcription factor, controlling its transcriptional activity can be a major target for anti-cancer drug development." (PMID 32781788, 2020). "In contrast with its function in other cancers, the expression of AR in RCC is negatively correlated with cancer development and survival rate; however, some reports show that the AR level influences the initiation and metastatic route of RCC." (PMID 32847068, 2020). "This study reinforces the utility of large cell line panels for the study of cancer and identifies several cell lines that represent ideal models to study AR-null cells that have upregulated GR to sustain growth." (PMID 33303959, 2020). "AR and GR expressions were observed in the nucleus and cytoplasm of residual cancer cells and stromal cells in prostate tissues, whereas ERα and PR expressions were expressed mainly in the stromal cells of prostate tissues." (PMID 32293349, 2020). "The molecular chaperone HSP 90 is involved in protein folding and maintaining protein stability (including AR) and has been reported to be overexpressed in many cancers, including PCa." (PMID 32878211, 2020). "A recent study has demonstrated that >78% AR positivity is required to accurately assess the prognostic role of AR in ER+ cancers, with ER+ patients that have ≥78% AR positivity having the best survival outcomes." (PMID 33062889, 2020). "There is hope that these novel agents, including seviteronel, will be effective in patients with AR+ cancers, including TNBC." (PMID 32117061, 2020). "The AR functions in cell migration and cancer metastasis by regulating its major target genes E-cadherin (CDH1) and vimentin (VIM)." (PMID 32847068, 2020). "The receptors often involved in mechanisms that lead to cancer progression are estrogen receptors (ER) and androgen receptors (AR)." (PMID 33552000, 2020). "Only 7.7% and 1.8% of AR-negative, but 33.1% and 13.1% of strongly AR expressing cancers showed a moderate or strong SFRP4 immunostaining (p < 0.0001)." (PMID 32677026, 2020). "Here we demonstrate that the imidazoacridinone C-1311 has a potent anti-cancer activity that extends to AR-dependent and AR-independent PCa cells." (PMID 32825120, 2020). "While the multiple AR pro-cancer functions have been well studied, its role in metastasis is poorly understood." (PMID 32296610, 2020). "Androgen receptor suppression induces autophagy, which further promotes cancer cell motility by increasing the disassembling of paxillin at focal adhesions." (PMID 32630699, 2020). "The genomic and pharmacologic stimulation and inhibition of AR activity demonstrates that AR regulates alternative splicing within cancer-relevant genes." (PMID 32820253, 2020). "In particular, several mechanisms are involved in the anti-PCa actions of these molecules, including inhibition of androgen receptor (AR) axis and targeting of cancer stemness." (PMID 32085497, 2020). "To evaluate combined HDAC inhibition with SARM administration as improved anti‐cachectic therapy, we designed a series of five studies combining AR‐42 with androgen/SARM in mouse models of cancer wasting." (PMID 31930715, 2020). "The studies on ligand-independent activation of AR in cancer is gradually increased in the recent years." (PMID 31896509, 2020). "Based on our results, it is possible that KDM7A controls AR activity as an epigenetic co-activator during cancer progression." (PMID 32781788, 2020).
cancer (continued). "We proposed that selective modulation of AR to prevent expression of genes promoting cancer while retaining expression of genes for normal processes would slow progression, reduce selection pressure, and delay resistance." (PMID 32198885, 2020). "Previous studies performed at our institutions demonstrated X-chromosome polysomy paralleled by AR gene copy number gain in most invasive MBC, as well as in in situ carcinoma and in cancer-associated gynecomastia." (PMID 32626651, 2020). "Although AR has crucial roles in many types of cancer, as shown by sex difference, the influence of AR was less understood in PTC." (PMID 32365531, 2020). "Suppression of androgen receptor signaling augments the cancer stem cell population with high invasive properties." (PMID 32630699, 2020). "In the presence of AR, the loss of HULLK significantly decreased cancer cells proliferation, whereas the overexpression of HULLK increased the sensitivity of PCa cells to AR in CRPC." (PMID 32164712, 2020). "PIN1 regulates HER2, NOTCH1, NOTCH3, androgen receptor (AR) and estrogen receptor α (ERα), which are cancer-driving receptors." (PMID 32258027, 2020). "We confirmed that AKT and AR mediated the anti-cancer effect of brassicasterol using siRNA transfection." (PMID 32972001, 2020). "Evolution to an AR-independent cancer with features of NED is an increasingly recognized resistance mechanism to AR pathway inhibitors in a subset of patients with advanced and rapidly progressive CRPC." (PMID 32313004, 2020). "Studies have shown that VEGFA/VEGFR2 is an important signaling axis in CRPC which allows the cancer cells to survive, proliferate and metastasize in an AR-independent manner." (PMID 32198489, 2020). "The unfavorable prognostic effect of Sox2 was complementary to the favorable effects of AR, and independent from cancer stage at diagnosis." (PMID 33553286, 2020). "An adamantyl tag has been incorporated into several androgen receptor antagonists to generate a novel class of s SARDs of use in androgen-dependent cancer cell lines." (PMID 33339292, 2020). "During PCa development, androgen receptor (AR) acts as the primary mediator of growth and survival of cancer cells through different androgen-mediated mechanisms, which is the basis for the front-line treatment with androgen-deprivation therapy (ADT)." (PMID 32790767, 2020). "Significant increase in the protein expression from normal to hormone refractory PCa was reported previously, also correlating with the nuclear expression of AR in normal adjacent and cancer tissue." (PMID 32878211, 2020). "Brassicasterol exerts an anti-cancer effect in AR-independent cancer as well as in AR-dependent cells by AKT inhibiting." (PMID 32972001, 2020). "Correspondingly, MYC and AR are the other regulators, down-regulated when the cells are transformed into cancer cells." (PMID 32193399, 2020). "Due to the outlined overall inhibitory effect of androgens/AR on immune cells it is likely that they also influence the response to anti-cancer immune therapies." (PMID 32714315, 2020). "Brassicasterol exerted an anti-cancer effect in AR-independent cancer as well as AR-dependent cells by inhibiting AKT." (PMID 32972001, 2020). "Androgen inhibition belongs to the therapeutic arsenal to treat prostate androgen receptor (AR) positive cancers." (PMID 32635472, 2020). "MAGE protein is involved in cancer signaling pathways by interacting with the androgen receptor during cancer growth and progression." (PMID 33169789, 2020). "AR-V7 lacks the C-terminal androgen binding domain, which leads to the permanent activation of AR as a transcription factor and results in the promotion of cancer cell growth." (PMID 32555282, 2020).
cancer (continued). "Favorable prognosis was observed in patients presenting high expression of “luminal like” genes (AR, GATA3) and decreased survival was observed in patients expressing cancer stem cell-like (WNT11) or EMT-associated genes (MMP28)." (PMID 32708049, 2020). "Analysis of CNVs in the top-10 HCC cancer-related genes with focal CNVs showed a larger number of amplifications in MYC (4q12) in low AR-RNA patients (FDR = 0.07)." (PMID 33328560, 2020). "PPARγ and androgen receptor are both ligand‐activated nuclear receptors with important roles in normal prostate development and cancer progression." (PMID 33031638, 2020). "Here, we identified AR-MethSig spanning 1000 genomic regions in the mCRPC plasma; these segments appear to identify a subgroup of cancers characterized by a more aggressive clinical course and enriched for AR copy number gain." (PMID 32149736, 2020). "Surprisingly, while physiological levels of androgens promote growth, supraphysiological androgen levels (SAL) inhibit PCa growth in an AR-dependent manner by inducing cell senescence in cancer cells." (PMID 32650419, 2020). "Another major resistance mechanism involves a lineage alteration into AR-indifferent carcinoma such a neuroendocrine which is diagnostically characterized by robust 18F-FDG uptake and loss of AR signaling." (PMID 33163409, 2020). "Melanoma-associated antigen 11 (MAGEA11), originally identified in melanomas as a cancer germline antigen, has been shown to function as an AR co-activator." (PMID 30791431, 2019). "Androgen receptor (AR) is essential in the growth and development of both normal and cancer prostate gland." (PMID 31295943, 2019). "On the other hand, the tumoral transformation of a normal prostate cell to cancer is believed to occur accompanied by a switch from paracrine to cell-autonomous constitutive AR signaling." (PMID 31366128, 2019). "ATAD2 acts as a transcriptional co-regulator of estrogen receptor alpha and AR to promote the expression of genes driving cancer cell proliferation and survival." (PMID 31527644, 2019). "Co-targeting strategies strive to improve cancer outcomes by combining therapies that inhibit driver genes in AR, MAPK, and mTOR pathways and are of great interest, since they are among the most frequently altered." (PMID 31136301, 2019). "To understand the effect of AR in cancer cells, we have treated LNCaP and LAPC4 cells, two immortalized human PCa cells in vitro, with the synthetic androgen R1881 and then performed RNA-seq analyses." (PMID 31485472, 2019). "AR is a steroid hormone receptor playing a pivotal role in cancer through androgen-induced gene transcription and kinase-signaling cascade activation." (PMID 30943211, 2019). "In short, these results indicate that PRCAT38 is an AR-regulated, prostate lineage-specific transcript that is over-expressed in cancer." (PMID 31405024, 2019). "A significant inverse correlation between AR and NFκB pathway activity was observed in cancer-adjacent tissue (Pearson −0.9; p = 0.019), and in the small primary PCa group, a similar trend was observed (Pearson −0.8, p = 0.10)." (PMID 30733525, 2019). "Activation of these signaling molecules impacts the activity of AR through increasing its nuclear translocation and upregulation of p21 which ultimately leads to chemoresistance to many anti-cancer drugs, including docetaxel." (PMID 31426412, 2019). "Pre-clinical studies have demonstrated the anti-cancer potential of curcumin via its effects on androgen receptor (AR) signaling and downstream targets (e.g., VEGF, PTEN, and NF-kB)." (PMID 31569529, 2019). "In fact, Giridhar and coworkers have shown that these cancer stem cells exhibit an AR- signature, related to the effect in these cells of MDM2 promoting the constant ubiquitination and degradation of AR, resulting in a consistent loss of AR protein." (PMID 31366128, 2019).
cancer (continued). "Despite the initial response, for a significant proportion of affected individuals, cancer cells develop castration resistance (CRPC) due to an aberrant androgen receptor (AR) expression and activation of intra tumoral androgen biosynthesis." (PMID 31652275, 2019). "In our study, RT-PCR was used to verify the expression level of AR mRNA, and in 4 paired clinical GC samples, the expression of AR was, indeed, higher in cancer tissues than in adjacent tissues." (PMID 31413736, 2019). "Medical castration (commonly referred to as hormonal treatment or androgen deprivation therapy (ADT)), blocks production of the hormone testosterone and/or targets the androgen receptor (AR) signalling axis that drives cancer cell growth." (PMID 31857319, 2019). "Patients with AR+ cancers were more likely to have smaller, lower-grade tumors, with higher expression of ER and PR." (PMID 30795773, 2019). "Further studies are required to assess its potential role in cancer progression, especially given our data showing AR 3′UTR as a region positively regulated by oncogenic miRs." (PMID 31043708, 2019). "Several C-C motif ligand (CCL)-receptor (CCR) axes are involved in cancer cell migration related to blockade of androgen/AR signaling." (PMID 30871130, 2019). "The amount of residual androgens is substantial for triggering androgen receptor (AR) signaling, AR target gene expression, and cancer cell proliferation." (PMID 31052459, 2019). "The fact that AR expression plays some cancer-immunological role in ER-positive breast cancer is enhanced by this report, which can add a novel aspect to future research and treatment of ER-positive breast cancer." (PMID 31151151, 2019). "We diagnosed the five nodules as lung metastases from docetaxel-resistant CRPC with few AR-signaling-dependent cancer cells." (PMID 31185946, 2019). "The phosphorylation of GSK-3β by AKT mediates abnormal expression of β-catenin and β-catenin has impact on the transactivation of AR to drive the progression in cancer." (PMID 31126320, 2019). "Vitamin D regulates signaling pathways such as the Wnt/β-catenin, estrogen receptor, and androgen receptor in the colon, breast, and prostate, respectively, which subsequently affect the growth of cancer in each tissue." (PMID 31126256, 2019). "We have discovered a previously unrecognized, fundamental tenet of PC, one which explains how and why AR signaling is different in cancer and benign cells." (PMID 31520575, 2019). "Studies have found that insulin-like growth factor receptor 1 (IGFIR), AKT, androgen receptor (AR), and cell proliferation and anti-apoptotic proteins are increased in cancer, but quercetin supplementation normalizes their expression." (PMID 30901869, 2019). "Most patients with PC respond to androgen-ablation therapies, which exploit the androgen-sensitivity of PC cells by either lowering serum androgen levels or blocking androgen receptor (AR) activity, resulting in apoptotic cancer cell death." (PMID 31583122, 2019). "In AR-positive cancer cell lines, resveratrol induced a biphasic effect on DNA synthesis—physiological concentration of resveratrol increased DNA synthesis, while higher concentrations inhibited DNA synthesis." (PMID 30823649, 2019). "Our findings indicate that JQ1 likely interrupts the crosstalk between AR and the cell cycle machinery, thereby suppressing the effect of AR on cancer cell survival." (PMID 31527644, 2019). "Although AR constitutes the main character in cancer development, a number of AR-mediated pathways were found to interact with other intracellular networks that are critically implicated in the PCa setting, especially in advanced phases." (PMID 31013746, 2019). "Its close-related partner FKBP51 is also overexpressed in this type of cancers and shows the ability to stimulate AR activity, the immunophilin being itself a product of the AR activity." (PMID 30717249, 2019).